CDH1 (cadherin 1)
Diseases named in the same sentence as CDH1 in open-access papers (continued):
Sharing a sentence is not in itself a finding about the gene and the disease.
lung carcinoma (continued). "For example, the XIST–EZH2 axis involves XIST recruiting EZH2 to mediate H3K27me3-dependent silencing of CDH1 and KLF2, which promotes the proliferation and migration of lung cancer cells." (PMID 41394878, 2025). "Next, the GSEA analysis was conducted using a gene set comprising CDH1, CDH2, and CDH3 to investigate their collective role in lung cancer." (PMID 40860670, 2025). "Our research into identifying new target genes for lung cancer therapy within the framework of external stimuli has brought to light two prominent candidates: AURKA downregulation and Cadherin 1 (CDH1) upregulation, also known as E-cadherin." (PMID 38707537, 2024). "Herein we show that AMPK activation by metformin relieves the repressive H3K9me2-mediated silencing of epithelial genes (e.g., CDH1) during EMT processes and inhibits lung cancer metastasis." (PMID 36872368, 2023). "Additional research conducted on sulforaphane demonstrated its ability to act as an epigenetic modulator of miR-21 and decrease CDH1 and DNMT protein levels in A549 lung cancer cells." (PMID 37568796, 2023). "It has been more than 20 years since CDH1 and CDH13 methylation were identified in lung cancer, so more insight has been gained into the involvement of both genes’ methylation in lung cancer." (PMID 37901797, 2023). "In lung cancer cells, BCRP is enriched inside the nucleus and binds to the E-box region of the E-cadherin (CDH1) gene promoter to regulate its transcription." (PMID 35883702, 2022). "Here, we found that FOXA1 knockdown decreased CDH1 (epithelial marker) but increased CDH2, VIM, SNAI2, and PTHLH (mesenchymal markers) in A549 lung cancer cells." (PMID 35897813, 2022). "Consistent with this, suppression of ID1 increased promoter occupancy of TCF4 and TWIST1 on E-box containing CDH1 and CDH2 promoter loci, and increased TCF4 and TWIST1 were observed on CDH1 and CDH2 promoters in FOXA1 knockdown A549 lung cancer cells." (PMID 35897813, 2022). "lncRNA MEG8 (human chromosome 14q32) overexpression in lung cancer and PDAC suppresses miR-34a and miR-203 expression, thereby upregulating the transcription factors SNAI1 and SNAI2, consequently repressing cadherin 1/E-cadherin expression." (PMID 36452037, 2022). "As an epithelial marker, CDH1, was decreased and mesenchymal markers, CDH2, VIM, SNAI2, and ITGA5 were increased in PGC1α-silenced epithelial types of A549, H358, and Calu-1 lung cancer cells." (PMID 33917757, 2021). "Previous work by others reported that, in the presence of brachyury, expression of E-cadherin (CDH1) was down-regulated, thereby promoting EMT in lung cancer cells." (PMID 34654834, 2021). "On the other hand, in lung cancer cells, RBBP7 acts as a transcriptional activator of the E-cadherin/CDH1 gene by binding to its promoter region thereby repressing EMT progress." (PMID 31636385, 2020). "Profiling the epithelial‐mesenchymal transition‐related molecular markers demonstrated decreased CDH1, TJP1, and OCLN and increased ZEB1, FN1, and EZH2 in response to CDKN2A silencing in lung cancer cells." (PMID 33155773, 2020). "The methylation status of RASSF1A, CDH1, DLC1 and PRPH was analysed in BW samples from 91 lung cancer patients and 31 controls, using a novel two‐colour droplet digital methylation‐specific PCR (ddMSP) technique." (PMID 32441866, 2020). "Aberrant hypermethylation phenotype of tumor suppressor genes by DNMT3a activity has been reversed by expression of miR-101-3p in a model of lung cancer, where DNMT3 repression led to promoter hypomethylation and re-expression of tumor suppressor CDH1." (PMID 31864341, 2019). "CXCR4, CK7, CDH1, CTNNB1 and HIF1A showed significant upregulation in primary lung cancer as compared to liver metastasis." (PMID 30383826, 2018).
lung carcinoma (continued). "Decreased expression of miR-200 up-regulates its target genes, namely CDH1 (also known as E-cadherin), VIM (also known as vimentin), ZEB1, and ZEB2, which leads to EMT as lung cancer progresses." (PMID 28486418, 2017). "Through the regulation of ZEB (zinc finger E-box-binding homeobox) transcription factors (ZEB1 and ZEB2), E-cadherin (CDH1), vimentin (VIM), the down-regulated miR-200 family promotes EMT in the progression of lung cancer." (PMID 27005669, 2016). "In the present study, 31 brain metastases that originated from primary lung carcinomas were analyzed regarding over expression of Dishevelled-1 (DVL1), Dishevelled-3 (DVL3), E-cadherin (CDH1) and beta-catenin (CTNNB1)." (PMID 24933634, 2014). "In this study, we found that knockdown of JARID2 antagonized TGF-ß-induced EMT of A549 lung cancer cell line and HT29 colon cancer cell line by inhibiting TGF-ß-dependent changes in expression of EMT-related genes such as CDH1, ZEB family and miR-200 family." (PMID 25542019, 2014). "In gene expression profiling studies of lung cancer cell lines to study therapeutic drug sensitivity, PLAU and CDH1 have been suggested as novel biomarkers of cetuximab sensitivity, and TGM2 was suggested as a potential marker of doxorubicin sensitivity." (PMID 20142997, 2010). "In multiple lung cancer cell lines, knockdown of either UBE2C or CDH1 significantly extended the protein half-life of DEPTOR, while ectopic overexpression of UBE2C or CDH1 shortened the protein half-life of DEPTOR." (PMID 36548081, 2023). "Similarly, decreased CDH1 and increased CDH2 were observed in FOXA1-silenced H358 lung cancer cells." (PMID 35897813, 2022). "In addition, ectopic FOXA1 expression significantly reversed TGFβ1-mediated expression of EMT markers, such as CDH1, CDH2, VIM, SNAI2, and PTHLH, in A549 lung cancer cells." (PMID 35897813, 2022). "Thus, we also performed a functional study of CRISPR/Cas9-mediated lncCDH5-3:3 knockout (KO), and overexpression outcomes on the CDH1 and EPCAM expression, cell cycle, proliferation, and apoptosis in lung cancer cells." (PMID 35159188, 2022). "Results from multiple studies in lung cancer suggest that epithelial phenotype with increased ECAD gene (CDH1) or protein expression, as opposed to mesenchymal or EMT phenotype, is associated with increased sensitivity to EGFR inhibitors." (PMID 34890102, 2022). "Lung cancer cell lines (HCC827 and PC9) exhibited a relatively high CDH1 mRNA expression." (PMID 34638565, 2021). "Specifically, FOXF1 could regulate the transcriptional activity of CDH1 by acting on its FOXF1-binding site, eventually contributing to cell migration and invasiveness in lung cancer." (PMID 32370197, 2020). "While CDH1 depletion caused a minimal, if any, effect on the levels of SKP2 in two lung cancer cell lines, it did not affect FBXW2-induced SKP2 reduction at all." (PMID 28090088, 2017). "A recent study demonstrated that a transposase (Tnp) of Acinetobacter baumanii was targeted to the nuclei of A549 (a human lung carcinoma) and COS-7 (African green monkey kidney) cell lines, and that this resulted in specific CpG methylation of the CDH1 (E-cadherin) promoter." (PMID 24723914, 2014). "Taken together, these studies demonstrate a remarkable upregulation of CDH1 in AD and SQ cells, but not LC and SC cells, making this a candidate marker for differentiating lung cancer subtypes." (PMID 20142997, 2010). "Two patients (P003 and P006) who met Amsterdam criteria, whose families suffered from colorectal cancer, lung cancer and bladder cancer, were not identified as MMR mutation carriers, but they carried many other tumor-associated genes, such as BRCA2, CDH1, MET, ATM, NF1." (PMID 35372080, 2022).
lung carcinoma (continued). "To examine whether the induction of EMT reduces HER2 expression, we analyzed mRNA expression of ERBB2, epithelial phenotype markers CDH1, EPCAM, MUC1 and OCLN, mesenchymal phenotype markers CDH2, FN1, SNAI2, and VIM in the A549 cell line (HER2-high human lung cancer epithelial cell line)." (PMID 34575017, 2021). "Similarly, MARVELD3 silencing decreases CDH1 and increases SNAI2 expression in lung cancer." (PMID 32260415, 2020). "Quantitative gene expression patterns of CXCL12, CK7, CDH1, CTNNB1, HIF1A, MUC16, TGFBR2 and CD44v6 were analyzed from CTC, exosomes and cell free RNA of lung cancer patients with and without liver metastasis." (PMID 38877052, 2024). "CXCL12, CK7, CDH1, CTNNB1, TGFBR2 and CD44v6 were upregulated in CTC as well as cfRNA whereas all these genes were downregulated in exosomes of primary lung cancer with and without metastasis." (PMID 38877052, 2024).
ovarian carcinoma (510 papers, 2003 to 2026). A malignant neoplasm originating from the surface ovarian epithelium. "A panel for hereditary breast and ovarian cancer including CDH1 was performed: a germline pathogenic splice variant of CDH1 c.1901C>T; r.1900_1936del; p.(Ala634Profs*7) was detected." (PMID 37761816, 2023). "For example, in ovarian carcinoma cells, reduced transcription of CDH1, which encodes E-Cadherin, is associated with hypermethylation in the presence of TGFβ." (PMID 36267157, 2022). "Among the differentially expressed gene that were associated with ovarian cancers, Cdh1, encoding E-Cadherin, was strongly downregulated in Runx1 KO ovaries." (PMID 36430923, 2022). "Downregulation of Cdh1 impairs epithelial cell adhesion and is associated with ovarian epithelial cancer." (PMID 36430923, 2022). "As we did not have genetic data on variants in the BRCA1/BRCA2 genes predisposing for hereditary breast and ovarian cancer or the CDH1 gene predisposing for hereditary diffuse gastric cancer, we excluded these families from the FCCTX cohort." (PMID 32321466, 2020). "High methylation of cadherin 1 promoters is a potential biomarker for prediction of ovarian cancer risk." (PMID 28881822, 2017). "A significant association was observed between CDH1 promoter methylation and ovarian cancer among 8 studies (OR = 8.71, 95 % CI = 4.87 - 15.58, P < 0.001), including 435 malignant tissues from ovarian cancer and 255 nonmalignant tissues." (PMID 27067410, 2016). "So the current meta-analysis was performed to identify the association between CDH1 promoter methylation and ovarian cancer risk." (PMID 27067410, 2016). "CDH1 promoter methylation can be a potential biomarker in ovarian cancer risk prediction, especially Asians can be more susceptible to CDH1 methylation." (PMID 27067410, 2016). "The findings showed that CDH1 promoter methylation had an increased risk of ovarian cancer in cancer tissues (OR = 8.71, P < 0.001) in comparison with nonmalignant tissues." (PMID 27067410, 2016). "The CDH1-160C>A (rs16260) polymorphism, located in the promoter region of the gene, can influence gene expression levels and has been associated with various cancers, including breast, bladder, and ovarian cancer." (PMID 40416864, 2025). "CDH1 promoter methylation is significantly associated with ovarian cancer risk." (PMID 27067410, 2016). "Secondly, the total sample size was not sufficient larger (less than 1000), our results may be lack vigorous power to evaluate the associations between CDH1 promoter methylation and ovarian cancer risk." (PMID 27067410, 2016). "However, the association between CDH1 promoter methylation and ovarian cancer remains to be certified." (PMID 27067410, 2016). "Furthermore, we identified c.8187G>T as a characteristic mutation of BRCA2 in the Chinese population, and the CHEK2 mutation was significantly associated with the early onset of ovarian cancer, while the CDH1 and FAM175A mutations were more prevalent in Northeast China." (PMID 38817903, 2024). "The heatmap revealed that PIWIL1, DNMT3B, OCT4, NANOG, and CDH2 were increased in most ovarian cancer samples, while CDH1 was downregulated, thus delineating clear expression differences between cancer and control samples." (PMID 41596471, 2026).
ovarian carcinoma (continued). "Functionally, TGFBI affected the migration and invasion of ovarian cancer cells by regulation of epithelial mesenchymal transition (EMT) markers (CDH1 and CDH2) and extracellular matrix (ECM) degradation proteins (MMP-2)." (PMID 38395907, 2024). "We report eleven families (47 CDH1 carriers) from our oncogenetic department specialized in breast and ovarian cancer, including four incidental findings." (PMID 37761816, 2023). "A panel for hereditary breast and ovarian cancer including CDH1 was performed: a large deletion leaving only the first two exons of CDH1 was detected (c.(163+1_164-1)_(*1_)?" (PMID 37761816, 2023). "Among the cancers examined, the levels of CDH1 mRNAs only exhibited significant downregulation between stage 2 and stage 3 of ovarian cancer." (PMID 37189027, 2023). "Sequestering miR-106a by circ-ITCH to upregulate CDH1 expression inhibits invasion and glycolysis of ovarian cancer cells." (PMID 35327551, 2022). "It showed that DNA methylation changes of CDH1, EPCAM and TWIST2 genes underlie the EMT induction in cisplatin resistant ovarian cancer cell line." (PMID 35523936, 2022). "For example, circ-ITCH suppresses glycolysis of ovarian cancer cells by competitively sponging miR-106a to enhance the expression of E-cadherin (CDH1)." (PMID 35327551, 2022). "EMT induced an invasive phenotype in ovarian cancer cells through downregulation of CDH1 and up-regulation of CDH2 in Hey and OVCA433 cells." (PMID 35523936, 2022). "For example, several markers such as CD133, ALDH1/2, LY6A, LGR5, EpCAM, CD133, CD44, CD34, CD24, CD117, MyD88, and CDH1 have been used for the isolation of CSCs from ovarian cancer cell lines." (PMID 35250573, 2022). "Our findings are similar to the study reported by Huang and colleagues who showed the phenotypic EMT characterization of 43 ovarian cancer cell lines and found that CDH1 expression in the cytoplasm was correlated with an intermediate mesenchymal phenotype." (PMID 34359774, 2021). "Next, we performed rescue assays to verify the regulatory effect of the circ-ITCH/miR-106a/CDH1 axis on ovarian cancer progression." (PMID 32714095, 2020). "In accordance with previous results, we demonstrated that CDH1 was notably down-regulated in ovarian cancer cells." (PMID 32714095, 2020). "Subsequently, we examined the protein expression of CDH1 in ovarian cancer cell lines by western blot." (PMID 32714095, 2020). "As a cell adhesion transmembrane glycoprotein or tumor suppressor, the E-cadherin gene (CDH1) has been reported to be an important regulator of ovarian cancer." (PMID 32714095, 2020). "All of these data indicated that circ-ITCH hindered the progression of ovarian cancer by miR-106a/ CDH1 axis." (PMID 32714095, 2020). "In our study, miR-106a directly targeted CDH1 and inversely regulated its expression in ovarian cancer cells." (PMID 32714095, 2020). "We found that CDH1 protein expression was significantly retarded in ovarian cancer cell lines A2780 and OVCAR3 than that in normal cell line ISOE80." (PMID 32714095, 2020). "Circ-ITCH suppressed proliferation, invasion, glycolysis, and promoted apoptosis of ovarian cancer cells by modulating the miR-106a/CDH1 axis." (PMID 32714095, 2020). "Hypermethylation of CDH1 promotor as well as transcriptional silencing was found in breast and ovarian cancer cell lines with inherent or acquired doxorubicin resistance." (PMID 30653577, 2019). "Our study results indicate the effects of methylation changes in ovarian cancer development and suggest that the CDH1 gene is a potential candidate for non-invasive diagnosis of ovarian cancer." (PMID 31450846, 2019).